MDM2 (MDM2 proto-oncogene)
Diseases named in the same sentence as MDM2 in open-access papers (continued):
Sharing a sentence is not in itself a finding about the gene and the disease.
cancer (continued). "Although GSK2830371 is a weak inhibitor of proliferation on different cancer cell lines, it dramatically potentiates the effect of MDM2 inhibitors, especially in cells where there is a WIP1/PPM1D overexpression or hyperactivation." (PMID 30689917, 2019). "We propose that the HBP1-dependent functions of MDM2 should be considered in the design of anti-cancer drugs." (PMID 30816344, 2019). "In particular, two networks directly related to cancer presented MDM2, ICAM1, and FTH1 as central nodes." (PMID 30925701, 2019). "A number of manuscripts have suggested that blocking both MDMX and MDM2 is an ideal goal for cancer treatment." (PMID 31489110, 2019). "Few studies have focused on the relationship between MDM2 and TKIs in malignancies while some studies have shown that combination of MDM2 inhibitors and the corresponding TKIs have synergistic effects on cancer treatment." (PMID 31440117, 2019). "DS‐5272, the MDM2 inhibitor used in this study, is known to have 4‐to‐5‐fold high activity than Nutlin‐3a to inhibit the growth of cancer cells in vitro." (PMID 30564368, 2019). "In fact, Giridhar and coworkers have shown that these cancer stem cells exhibit an AR- signature, related to the effect in these cells of MDM2 promoting the constant ubiquitination and degradation of AR, resulting in a consistent loss of AR protein." (PMID 31366128, 2019). "We found an increased number of CTCs when MDA-MB-231 cancer cells expressed high levels of both MDM2 and MDMX." (PMID 30642351, 2019). "For example, MDM2- and MDM2-associated eRNA (MDM2e, ENSR00000053727) are positively correlated in 12 cancer types, and Hi-C data supports their chromatin interaction in 20 tissues." (PMID 31594934, 2019). "Both the PI3K/Akt and MAPK pathways can phosphorylate MDM2 on serine residues 166 and 186 to promote the oncogenic function of MDM2 in cancer cells." (PMID 31921839, 2019). "Ruiwen Zhang (University of Houston) presented his research on developing dual inhibitors for inflammatory factor NFAT1 and MDM2 for cancer prevention and treatment." (PMID 31408158, 2019). "The small molecule RG7388 (idasanutlin, R05503781) is a newly developed inhibitor that is specific for an oncogene-derived protein called MDM2, which is also in clinical trials for the treatment of various types of cancers." (PMID 30700046, 2019).
cancer (continued). "The identification of MDM2 overexpression leading to an inhibition of DNA break repair and causing cell death by repressing HBP1 also opens up new therapeutic avenues for cancer therapy." (PMID 30816344, 2019). "As an oncogene that commonly is over-expressed in human cancers, MDM2 represents a novel target for cancer therapy." (PMID 31779710, 2019). "Douglas Fang (Ascentage Pharma) shared data on a promising combination cancer therapy with MDM2 antagonist APG-115 and immune checkpoint blockade." (PMID 31408158, 2019).
cancer (continued). "Structure-activity relationship studies lead to the discovery of a refined Nutlin-3-derived compound, RG7112, which is the first MDM2 inhibitor advanced into clinical trials for the treatment of several human cancers." (PMID 30134553, 2018). "Currently, the majority of cancer therapeutics have been developed to target a single molecular target or pathway, such as β-catenin and MDM2." (PMID 29387014, 2018). "In cancer cells, p73 transcription activity is abrogated, among other mechanisms, by binding to MDM2 or MDMX (human MDM4)." (PMID 30603043, 2018). "The majority of cancer types included a subgroup of patients, albeit small, with MDM2 amplification." (PMID 30148248, 2018). "This gives hope for the development of combined strategies that would not only prevent the development of secondary resistance, but also deal with cancer cells, which acquire resistance to MDM2 antagonists." (PMID 30352966, 2018). "Our findings offer strong supporting evidence that MDM2 can impact growth and metastatic potential of cancer cells through tilting the balance towards pro-angiogenic mechanisms." (PMID 29748481, 2018). "Ponatinib thus affects cancer cell growth by blocking the FGFR/AKT/MDM2 survival pathway, resulting in the activation of BIM-mediated apoptosis." (PMID 29899872, 2018). "It is envisioned that SP141 can be a useful tool to explore the β-catenin and MDM2 dual-targeting approach for cancer therapy." (PMID 29387014, 2018). "One of the ways to deal with the generation of secondary resistance is to enhance the elimination of cancer cells by combining MDM2 antagonists with additional anticancer treatments." (PMID 30352966, 2018).
cancer (continued). "An understanding of MDM2 amplification status has clinical relevance for patients with cancer because MDM2 inhibitors are in early-phase clinical development." (PMID 30148248, 2018). "In cancers, the binding of free RPs to MDM2 has been shown to mediate the response to ribosomal-stress-inducing chemotherapeutics such as actinomycin D and 5-fluorouracil." (PMID 29530001, 2018). "Amplification of mdm2 has been observed in more than 10% of human cancers and has been found sufficient to induce tumorigenesis." (PMID 29464071, 2018). "DM chromosomes have a predisposition to involve cancer oncogenes such as MYC proto-oncogene protein (MYC), MDM2 proto-oncogene (MDM2) or cyclin-dependent kinase 4 (CDK4)." (PMID 29616301, 2018). "In the current study, we identified Nutlin‐3a, a classic MDM2 inhibitor, with unexpected drug effect in CTNNB1‐mutated cancer cells." (PMID 29532999, 2018). "Despite extensive data on MDM2 dysregulation in cancer, little is known about the characteristics of patients in whom MDM2 gene expression is altered or amplified." (PMID 30237864, 2018).
cancer (continued). "CDK4, a cancer gene 10 Mb proximal to MDM2 in both human and canine genomes and often the target of bipartite amplification alongside MDM2, was co-amplified in three of these cases." (PMID 30188888, 2018). "To investigate if PpIX can inhibit TAp73/MDM2(X) interactions also in cancer cells, we immunoprecipitated TAp73 after treatment with PpIX and blotted the membrane with MDM2 or MDMX antibodies." (PMID 30603043, 2018). "A newly developed inhibitor, RG7388 specific for an oncogene-derived protein called MDM2, is in clinical trials for the treatment of various cancers." (PMID 30583560, 2018). "Given the clinical importance of MDM2, we describe the landscape of cancer types that harbor MDM2 amplification and evaluate the comprehensive genomic profiles of 102,878 tumors from patients with malignancies." (PMID 30148248, 2018). "TAp73 is found inactivated in cancers by binding to oncogenic ΔNp73, MDM2 and MDMX proteins or by degradation by the ubiquitin ligase Itch." (PMID 30603043, 2018). "We used next-generation sequencing (NGS) to ascertain MDM2 amplification status across a large number of diverse cancers." (PMID 30148248, 2018). "It is worth noting, however that a variety of cancer types that express MDM2-FL and different MDM2 isoforms still undergo cell death when exposed to MDM2 antagonists." (PMID 29065514, 2017). "A recent study using improved methods of detecting MDM2 amplification suggests low frequencies (~10%) of MDM2 gene amplification in the majority of various types of cancers, including those in childhood." (PMID 28054974, 2017). "The authors detected distinct Mdm2-dependent gene regulatory patterns when comparing primary cells, stem cells, and cancer cells in high-throughput transcriptome studies, suggesting system-dependent differences in Mdm2 functions." (PMID 27927750, 2017). "The concentration and activity of р53 cancer suppressing protein in a cell is controlled by MDM2 protein, which inactivates and accelerates degrading of р53 cancer suppressing protein, thus, hampering DNA reparation and, therefore, promotes, carcinogenesis." (PMID 29132330, 2017).